HKDC1 (hexokinase domain containing 1)
Diseases named in the same sentence as HKDC1 in open-access papers (continued):
Sharing a sentence is not in itself a finding about the gene and the disease.
preeclampsia (1 paper, 2022). Preeclampsia is a hypertensive disorder of pregnancy that is characterized by new-onset hypertension with proteinuria presenting after 20 weeks of gestation, and depending on mild or severe forms may initially present with severe headache, visual disturbances, and hyperreflexia. "Furthermore, the fact that variants within HKDC1 are associated with glucose levels in pregnant women and considering the relationship between abnormal glucose levels and preeclampsia, it is also possible that natural selection has targeted variants at HKDC1 due to its role in glucose metabolism." (PMID 35460423, 2022).
renal fibrosis (1 paper, 2022). A final common manifestation of a wide variety of chronic kidney diseases characterized by glomerulosclerosis and tubulointerstitial fibrosis. "By targeting the COL28/HKDC1 signaling pathway, this provides a unique therapeutic approach for the treatment of renal fibrosis." (PMID 36518326, 2022). "In fibrotic renal tissue, expression of COL28 is significantly increased, and overexpression of COL28 further exacerbates renal fibrosis by promoting EMT through increased expression of SREBP1 and HKDC1." (PMID 36518326, 2022).
Sepsis (1 paper, 2025). Sepsis is defined as life-threatening organ dysfunction caused by a dysregulated host response to infection. "To evaluate the role of HKDC1 in inflammatory diseasesin vivo, we established an LPS-induced mouse sepsis model on the basis of protocols described in the literature." (PMID 40692442, 2025). "HKDC1 interacts with heat shock cognate B (HSCB) and ferredoxin 1 (FDX1), leading to increased intracellular copper levels and subsequent cuproptosis.HKDC1 knockdownin vivo alleviates acute sepsis by activating copper-dependent cell death pathways." (PMID 40692442, 2025).
cancer (33 papers, 2014 to 2026). A tumor composed of atypical neoplastic, often pleomorphic cells that invade other tissues. "These divergent outcomes highlight the intricate role of HKDC1 in cancer prognosis and underline the necessity for additional investigations to elucidate its context-dependent effects across various cancer types." (PMID 40124623, 2025). "In recent years, cancer investigations have increasingly focused on the prognostic significance of HKDC1, showing that its expression levels are closely associated with patient outcomes." (PMID 41049000, 2025). "To assess the clinical relevance of HKDC1 expression across various cancers, we performed a comprehensive analysis of its association with patient outcomes, utilizing data from 33 cancer types sourced from the TCGA database." (PMID 40124623, 2025). "Although, HKDC1 is reported to be overexpressed in many cancers and high HKDC1 expression is associated with poor clinical outcome, how HKDC1 expression is regulated remains largely unclear." (PMID 40391325, 2025). "Our findings demonstrate that HKDC1 influences cancer cell proliferation, susceptibility to cell death, and ultimately intestinal carcinogenesis, potentially through interactions with mitochondrial proteins regulating membrane permeability." (PMID 40110992, 2025). "We conducted an exhaustive examination of both genetic and epigenetic modifications to investigate the mechanisms underlying the increased expression of HKDC1 in cancer." (PMID 40124623, 2025). "HKDC1 is a newly identified metabolic regulatory element, whose upregulation is tightly linked to metastatic competence across multiple cancers." (PMID 41049000, 2025). "Our findings revealed a substantial number of mutations distributed uniformly across the entire coding sequence of HKDC1 in diverse cancer types, suggesting a potential role for these mutations in modulating HKDC1 expression." (PMID 40124623, 2025). "On the other hand, abnormal expression of HKDC1 has been linked to the development of a wide variety of diseases and cancers." (PMID 37153834, 2023). "For example, HKDC1 has been previously shown to correlate with KRAS signaling in cancer cells, where loss of mutated KRAS expression led to an increased HKDC1 expression." (PMID 28039486, 2017). "HKDC1 has been linked to various mechanisms that promote cancer progression." (PMID 41049000, 2025). "Consequently, the association identified between HKDC1 and immune checkpoint expression in this research further emphasizes the potential importance of HKDC1 within the landscape of cancer immunotherapy." (PMID 40124623, 2025). "Among the significantly enriched pathways, we observed a notable association with glycolysis, indicating that HKDC1 may be involved in modulating cellular energy metabolism, a hallmark of cancer." (PMID 40124623, 2025). "From both functional and mechanistic viewpoints, GSEA has indicated that HKDC1 may be crucial in several essential cancer hallmark pathways and their related biological processes." (PMID 40124623, 2025). "Collectively, our GSEA offers an extensive overview of the prospective functional dynamics associated with HKDC1 across various cancer types, thereby laying the groundwork for subsequent explorations into its distinct roles and underlying mechanisms in diverse oncological contexts." (PMID 40124623, 2025). "A recent study indicated that HKDC1 functions as a glucose sensor within the tumor microenvironment, and its dysregulated expression has been associated with chronic inflammation and various cancers." (PMID 40110992, 2025). "There was growing evidence indicating the association between HKDC1 and cancer susceptibility." (PMID 33991070, 2021). "In addition, the normal cells have much less dependency on HKDC1/VDAC association-mediated normal metabolism compared with cancer cell lines." (PMID 32203147, 2020).
cancer (continued). "Here, we discovered a function of ZMAT3 in inhibiting transcription of HKDC1, a hexokinase that regulates glucose metabolism and mitochondrial respiration in human cancer cells." (PMID 41842937, 2026). "The primary objective of this study was to systematically evaluate the potential of HKDC1 as a biomarker across various cancer types." (PMID 40124623, 2025). "In summary, HKDC1 is a key player in cancer metabolic regulation and an important target for future cancer treatments and personalized medicine." (PMID 41049000, 2025). "Using TIMER2.0 and TCGA databases, we analyzed HKDC1 expression across multiple cancers and evaluated its prognostic value via Kaplan-Meier survival analysis." (PMID 40209953, 2025). "A recent study (Guo etal., 2022) emphasized that cancer cells exploit specific post-translational modifications of HKDC1 to inhibit its function during apoptosis, thereby facilitating the survival of malignant cells." (PMID 40124623, 2025). "The exploration of HKDC1's role in cancer offers potential for new therapeutic strategies and biomarkers in cancer treatment." (PMID 41049000, 2025). "In the present study, we performed in vitro experiments aimed at further elucidating the stimulatory role of HKDC1 in cancer-related processes." (PMID 40124623, 2025). "It indicating that HKDC1 is a promising therapeutic target for metabolic intervention in cancer treatment." (PMID 41049000, 2025). "This regulatory complexity indicates that HKDC1’s role in cancer metabolism extends beyond simple enzymatic activity and likely involves sophisticated regulatory mechanisms that remain incompletely understood." (PMID 40894906, 2025). "HKDC1 promotes the stem cell properties of cancer cells by binding to glycogen synthase kinase 3β (GSK3β), which stabilizes beta-catenin." (PMID 40124623, 2025). "Collectively, these studies position HKDC1 as both a biomarker of metastatic potential and a promising therapeutic target to curb cancer cell migration and invasion." (PMID 41049000, 2025). "Recent studies have identified aberrant overexpression of HKDC1 in various cancers, contributing to tumor progression." (PMID 40209953, 2025). "Our initial pan-cancer analysis provided a comprehensive understanding of the oncogenic roles of HKDC1 across diverse cancer types." (PMID 40124623, 2025). "By embracing this holistic viewpoint, our goal was to achieve an enhanced comprehension of the pervasive and possibly integrative function of HKDC1 in cancer, thereby aiding in the formulation of more focused and efficacious therapeutic approaches." (PMID 40124623, 2025). "Emerging evidence indicates that HKDC1 not only acts directly on cancer cells but also modulates the TME through immune cell infiltration and metabolic crosstalk." (PMID 41049000, 2025). "Previous investigations have documented HKDC1’s involvement in diverse malignancies, with studies demonstrating its participation in metabolic reprogramming processes across various cancer types." (PMID 40894906, 2025). "A comprehensive analysis of various tumor types has revealed that HKDC1 is significantly upregulated in many malignant tumors." (PMID 40124623, 2025). "Our findings indicate that Menin associates with YBX1, subsequently enhancing the transcription of HKDC1, a known regulator of cancer glycolysis." (PMID 40894906, 2025). "Our findings demonstrate that HKDC1 holds significant prognostic relevance across a diverse array of tumors, underscoring its potential as a valuable biomarker for cancer prognosis and therapeutic strategies." (PMID 40124623, 2025). "HKDC1 has emerged as a compelling biomarker for the early diagnosis of various cancers in recent years 22,26,30." (PMID 41049000, 2025). "In this study, we identified a significant correlation between HKDC1 expression levels and the infiltration of various immune cell populations within the tumor microenvironment across multiple cancer types." (PMID 40124623, 2025).
cancer (continued). "Collectively, these findings underscore the clinical importance of HKDC1 expression as a potential biomarker for cancer prognosis and as a promising target for therapeutic intervention." (PMID 40124623, 2025). "These discrepancies underscore the importance of elucidating the specific roles and processes underpinning HKDC1 regulation in individual cancer types." (PMID 40124623, 2025). "Among various cancer types, HKDC1 expression was highest in CRC, followed by pancreatic, renal, stomach, and liver cancer." (PMID 40110992, 2025). "HKDC1 is emerging as an important regulator of tumor progression and is frequently upregulated in several cancers including CRC51–53." (PMID 40391325, 2025). "HKDC1 enhances the migration and invasion capacities of cancer cells by reprogramming their metabolic landscape." (PMID 41049000, 2025). "This metabolic variation not only facilitates rapid proliferation but also supports in the survival of cancer cells under metabolic stress, underscoring HKDC1 as a promising therapeutic target for metabolic intervention in cancer treatment." (PMID 41049000, 2025). "Analysis using the TIMER2.0 database revealed elevated HKDC1 expression in several cancer types, notably CRC." (PMID 40209953, 2025). "Utilizing the XCELL algorithm, our results revealed a positive correlation between HKDC1 expression levels and the infiltration of diverse immune cell subsets in numerous cancers." (PMID 40124623, 2025). "Recent investigations across various cancer types have identified HKDC1 as a significant player in metabolic reprogramming, with studies in gastric, lung, and colorectal malignancies demonstrating its involvement in cellular glucose utilization." (PMID 40894906, 2025). "Collectively, these data indicated that aberrant HKDC1 expression in cancer cells promotes tumor immune evasion by increasing exhaustion of tumor-infiltrating CD8+ T cells." (PMID 38351096, 2024). "Aberrant expression of HKDC1, a recently identified human hexokinase, is closely correlated with overall survival in cancer patients." (PMID 38351096, 2024). "We also found an increase in HKDC1, which is a recently discovered hexokinase increased in various cancer cells." (PMID 38855868, 2024). "Much of the interest in HKDC1’s role in cancer stems from the fact that, like HK1 and 2, it localizes in the mitochondrial outer membrane (MOM) and binds with the voltage-dependent anion channel (VDAC)." (PMID 37109475, 2023). "This review focuses on the role of HKs, particularly HKDC1, in metabolic reprogramming and cancer progression." (PMID 37109475, 2023). "Supporting the observation that HKDC1 is overexpressed in LC, we mined TCGA data, which showed that HKDC1 is significantly upregulated in human cancers." (PMID 35902556, 2022). "Previous results from our group point to a role for HKDC1 as a mediator of circadian clock-induced metabolic phenotype rewiring in cancer cells and subsequent modulation of tumour progression and drug response." (PMID 36012399, 2022). "It has been reported recently that HKDC1 catalyzes glucose phosphorylation and cellular energy metabolism involving cancer growth and metastasis." (PMID 32943998, 2020). "Recent bioinformatics analysis has shown that HKDC1 is a novel potential therapeutic target for cancer." (PMID 31058090, 2019). "HKDC1 share structural homology with other hexokinases, essential enzymes governing glucose metabolism 8, yet possesses unique features suggesting distinct regulatory functions, potentially influencing metabolic pathways in cancer cells." (PMID 41049000, 2025). "Increasing evidence suggests that HKDC1 contributes to the progression of various cancers." (PMID 40209953, 2025). "These CNVs likely contribute to the deregulation of HKDC1 expression in cancer." (PMID 40124623, 2025). "HKDC1 could serve as a valuable biomarker for early cancer diagnosis, potentially facilitating its incorporation into routine clinical evaluations." (PMID 41049000, 2025).
cancer (continued). "In light of these observations, HKDC1 has emerged as a potential biomarker for cancer prognosis." (PMID 40124623, 2025). "Moreover, our findings reveal that, in most of the cancer types analyzed, HKDC1 expression is positively correlated with tumor stemness—an aspect previously associated with the promotion of tumor initiation, metastasis, and treatment resistance." (PMID 40124623, 2025). "Lastly, the notable enrichment in the Toll-like receptor signaling pathway highlights the potential role of HKDC1 in modulating immune responses and inflammatory processes, both of which are increasingly recognized as crucial factors influencing cancer development and therapeutic outcomes." (PMID 40124623, 2025). "Such efforts will advance our understanding of HKDC1's biological functions, we may unlock novel metabolic and immunotherapeutic approaches that transform cancer diagnosis and therapy in the future." (PMID 41049000, 2025). "Therefore, this review aims to synthesize current knowledge regarding HKDC1, including its structural attributes and its correlation with cancer metabolism reprogramming, thereby underscoring its research significance and clinical translational potential." (PMID 41049000, 2025). "Thus, deletion of HKDC1 in human colonic epithelial cells completely abolished their tumor‐forming ability, providing full protection against cancer development." (PMID 40110992, 2025). "Additionally, there is evidence that the increased expression of HKDC1 correlates with the advancement of tumor angiogenesis, along with heightened cancer invasion and metastasis." (PMID 40124623, 2025). "Conversely, we noted decreased HKDC1 expression in KICH, LUSC, PRAD, and THCA, suggesting that distinct cancer types may harbor varied underlying mechanisms that govern HKDC1 expression levels." (PMID 40124623, 2025). "Aberrant expression of the human hexokinase HKDC1 has been observed in patients with cancer." (PMID 38351096, 2024). "Evaluating similar inhibitors for HKDC1 could prove to be an effective therapeutic avenue for cancer treatment in the future." (PMID 37109475, 2023). "Additionally, there was a direct correlation between the degree of HKDC1 protein expression and histological differentiation, reduced survival, tumor size, pN (N refers to the number of nearby lymph nodes with cancer) stage, and poor prognosis." (PMID 37109475, 2023). "Beyond the metabolic functions, HKDC1 is differentially expressed in many forms of human cancer." (PMID 37109475, 2023). "In a variety of cancers, the hexokinase domain component 1 (HKDC1) is carcinogenic." (PMID 37153834, 2023). "In the future, the binding of HK2 and HKDC1 could be specifically targeted as a promising therapeutic strategy for effective outcomes in cancer." (PMID 37109475, 2023). "According to the findings of a recent analysis, HKDC1 is responsible for catalyzing glucose phosphorylation and the metabolism of cellular energy, both of which are critical in the development and spread of cancer." (PMID 37153834, 2023). "Several studies postulate a role for HKDC1 as a potential therapeutic target for different cancers." (PMID 36012399, 2022). "HKDC1 affects behavioral functions in cancers by different mechanisms." (PMID 32943998, 2020). "However, aberrant expression of HKDC1 contributes to the progression of certain types of diseases and cancers." (PMID 32943998, 2020). "Recent studies show that HKDC1 may be a novel potential therapeutic target for cancer, although the detailed mechanism behind the role of HKDC1 in this process remains unclear." (PMID 31058090, 2019). "It has been reported that HKDC1 catalyzes glucose phosphorylation and the related cellular energy metabolism involves with cancer growth and metastasis, although the potential role of HKDC1 in cancer development remains unclear." (PMID 31058090, 2019).